JAZF1 (JAZF zinc finger 1)
Description:
Acts as a transcriptional corepressor of orphan nuclear receptor NR2C2. Inhibits expression of the gluconeogenesis enzyme PCK2 through inhibition of NR2C2 activity (By similarity). Also involved in transcriptional activation of NAMPT by promoting expression of PPARA and PPARD (By similarity). Plays a role in lipid metabolism by suppressing lipogenesis, increasing lipolysis and decreasing lipid accumulation in adipose tissue (By similarity). Plays a role in glucose homeostasis by improving glucose metabolism and insulin sensitivity (By similarity).
Synonyms: TIP27; ZNF802; DKFZp761K2222
Tractability: PROTAC: ubiquitination databases record sites on it.
Gene: Protein-coding gene on chromosome 7 (27,830,573 to 28,180,992, reverse strand). Ensembl gene ENSG00000153814.
Subcellular location: Nucleus
Subcellular location (Human Protein Atlas): Nucleoli fibrillar center; Nucleoplasm; Cytosol; Primary cilium tip
Gene Ontology:
Molecular function: protein binding; transcription corepressor activity
Biological process: negative regulation of transcription by RNA polymerase II
Cellular component: nucleoplasm; transcription repressor complex; nucleus
Genetic constraint (gnomAD): Loss-of-function variants: 4 observed, 20.91 expected, observed/expected ratio (o/e) 0.19, 90% interval 0.093 to 0.44. The upper end of that interval is the gene's LOEUF score, 0.44, which puts it in group 1 of 6, group 1 being the genes least tolerant of losing a copy. Missense variants: 181 observed, 301.61 expected, observed/expected ratio (o/e) 0.6, 90% interval 0.53 to 0.68. Synonymous variants: 115 observed, 117.55 expected, observed/expected ratio (o/e) 0.98, 90% interval 0.84 to 1.14.
Homologues: Orthologues: chimpanzee JAZF1 (100% identical), dog JAZF1 (100% identical), pig JAZF1 (100% identical), mouse Jazf1 (99% identical), rat Jazf1 (99% identical), tropical clawed frog jazf1 (98% identical), zebrafish jazf1b (90% identical), macaque JAZF1 (86% identical), guinea pig JAZF1 (84% identical), zebrafish jazf1a (83% identical), rabbit JAZF1 (80% identical), Drosophila melanogaster CG12054 (51% identical).
Diseases named in the same sentence as JAZF1 in open-access papers:
JAZF1 is named in the same sentence as 71 diseases in open-access papers, as found by Europe PMC text mining. Sharing a sentence is not in itself a finding about the gene and the disease. The quoted sentences say what the papers report.
diabetes (30 papers, 2009 to 2025). "Under specific pathological conditions, downregulation of JAZF1 expression is observed, and this reduction in JAZF1 levels has been implicated in the pathogenesis of metabolic disorders such as obesity, diabetes, and hepatic steatosis." (PMID 40866818, 2025). "For example, instruments are from genes TCF7L2, IGF2BP2, NOTCH2, CDKAL1, PABPC4, FTO and JAZF1, known to be associated with diabetes and that have been further significantly associated with the metabolites." (PMID 39349772, 2024). "JAZF1 has been implicated in glucose and lipid homeostasis, insulin signaling, and metabolic disorders such as diabetes." (PMID 37091973, 2023). "Other T2D-associated SNPs have also been identified on JAZF1, many of which have additionally been linked to diabetes-relevant metabolic traits such as insulin secretion, insulin clearance, plasma lipid levels and body weight." (PMID 37091973, 2023). "Juxtaposed with another zinc finger protein 1 (JAZF1) is associated with metabolic disorders, including type 2 diabetes mellitus (T2DM)." (PMID 34407873, 2021). "Genotype GG of the JAZF1 variant was found significantly associated with the risk of developing type 2 diabetes mellitus in the Pakistani subset of the population." (PMID 33425511, 2020). "Various reports have shown that Jazf1 is associated with a variety of diseases, including cardiac disease, diabetes, endometrial stromal sarcoma, and prostate cancer." (PMID 29416651, 2018). "Numerous studies have shown that Jazf1 affects both diabetes and prostate cancer risk, and is highly expressed in aggressive prostate cancer." (PMID 29416651, 2018). "Studying the interactions between SNPs and diabetes was of particular interest since genetic variation in JAZF1 and TCF2 has been associated with both prostate cancer and diabetes." (PMID 21390317, 2011). "The major T-allele of the intronic JAZF1 rs864745 conferring increased diabetes risk was associated with increased 2nd phase serum insulin release during an IVGTT (p = 0.03), and an increased fasting serum insulin level (p = 0.001)." (PMID 19789630, 2009). "Carriers of the diabetes-associated T-allele of JAZF1 rs864745 had an allele dependent 3% decrease in BIGTT-AIR." (PMID 19789630, 2009). "Juxtaposed with another zinc finger protein 1 (Jazf1) contains three zinc finger motifs and is of unknown function but is associated with lipid metabolism, diabetes mellitus, and prostate cancer." (PMID 22475005, 2012). "Moreover, rs849334 of JAZF‐1 is significantly associated with insulin clearance, which could predict the progression of diabetes." (PMID 36734198, 2023). "This is further supported by the fact that many of the closely correlating protein-coding genes have themselves been previously implicated in diabetes, such as FAIM2, JAZF1, and XBP1, as well as others whose connections likely remain uncharacterized." (PMID 37218990, 2023). "JAZF1 (TIP27) has been mostly studied for its role in gluconeogenesis and lipid metabolism in relation to the development of type 2 diabetes mellitus, and its signalling also results in decreased expression of pro‐inflammatory cytokines." (PMID 36204213, 2022). "The JAZF1 and FIns of the Complication Group and Diabetes Group were lower than those of the Healthy Control Group, and JAZF1 of the Complication Group was lower than the Diabetes Group with statistical significance (P<0.05, respectively)." (PMID 33722242, 2021). "Several studies have demonstrated that JAZF1 is related to a diversity of diseases, including diabetes, cardiac disease, prostate cancer and endometrial stromal sarcoma." (PMID 31357957, 2019). "Previously, Jazf1 was mainly researched in the context of diabetes, because Jazf1 is a novel repressor of TR4, a kind of nuclear receptor that regulates gluconeogenesis." (PMID 29416651, 2018). "Jazf1 inhibits testicular nuclear receptor 4 (TR4) activation through protein-protein interaction, which results in weight loss and alleviates diabetes." (PMID 29416651, 2018).
diabetes (continued). "Furthermore, several genome-wide association studies suggest that diabetes mellitus and prostate cancer share certain genetic factors, including the HNF1β and JAZF1 genes, and a previous study suggested that JAZF1 might represent a potential target against diabetes and obesity." (PMID 23406686, 2013). "We observed marginally significant interactions between diabetes and rs10486567 in JAZF1 (P = 0.04) and between BMI and rs10486567 (P = 0.03)." (PMID 21390317, 2011). "Previous studies on the JAZF1 gene primarily focused on its role in diabetes and lipid metabolism." (PMID 40866818, 2025). "Both psoriasis and diabetes are associated with the PTPN22, ST6GAL1, and JAZF1 genes." (PMID 40660159, 2025). "As diabetes is a condition linked to increased cardiovascular risk, it was unsurprising that our work revealed gene interaction between KLFs, particularly KLF-14, and genes associated with diabetic risk factors, such as CAMK1D, HHEX, JAZF1, and TCF7L2." (PMID 38672763, 2024). "Therefore, this study aimed to shed light on the relationship between rs864745 in JAZF1 and T1D, T2D subgroups, and also β-cell function and lipid metabolism in both healthy and diabetes disease status." (PMID 35846288, 2022). "Obesity and diabetes status alter the JAZF1 expression pattern." (PMID 35846288, 2022). "It has been shown that some diseases, such as diabetes, obesity, and hepatic steatosis, may alter JAZF1 expression in tissues." (PMID 34440550, 2021). "We identified fourteen type 2 diabetes-associated genes discovered by the first waves of GWAS for which there was little prior evidence of their potential role in diabetes (Adam30, Adamts9, Camk1d, Cdc123, Cdkal1, Cdkn2a, Cdkn2b, Ext2, Hhex, Ide, Jazf1, Lgr5, Thada and Tspan8)." (PMID 23442068, 2013). "We did see a borderline statistically significant interaction between rs10486567 in JAZF1 and diabetes, but this particular SNP has not been associated with diabetes risk." (PMID 21390317, 2011). "The link between psoriasis and diabetes could, in part, be explained by the rise in obesity and unhealthy lifestyles, the insulin resistance associated with inflammation, and the presence of various genes (CDKAL1, PTPN22, ST6GAL1, JAZF1) linked to both conditions." (PMID 38541672, 2024). "The FPG, 2hPG, TG, HbA1C, CRP, IL-6, visfatin, JAZF1, HOMA-IR, baPWV, and EAT thickness of the Diabetes Group were all higher than those of the Healthy Control Group, with statistical significance (P < 0.05)." (PMID 33722242, 2021). "The FPG, 2hPG, HbA1C, CRP, IL-6, Visfatin, JAZF1, HOMA-IR, EAT thickness, and baPWV of the Complication Group were all higher than those of the Diabetes Group and the Healthy Control Group (P < 0.05, respectively)." (PMID 33722242, 2021). "JAZF1 as a transcriptional repressor of TR4, previous studies focused on JAZF1 function in gluconeogenesis regulation and diabetes." (PMID 31357957, 2019). "JAZF1 is also found playing an important role in prostate cancer and diabetes; however, the molecular mechanism by which JAZF1 acts in these diseases has not yet been clarified." (PMID 31357957, 2019). "The associations of 23 SNPs located within 17 candidate genes (MTHFR, PPARγ, LPL, INSIG, TCF7L2, FTO, KCNJ11, JAZF1, CDKN2A/B, ADIPOQ, WFS1, CDKAL1, IGF2BP2, KCNQ1, MTNR1B, IRS1, ACE) with overweight and obesity, diabetes, metabolic phenotypes, and MetS were examined in both studies." (PMID 24959828, 2014). "A previous study conducted in CPS-II and PLCO found that diabetes did not mediate the association between JAZF1 and HNF1B/TCF2 SNPs and prostate cancer risk, and we observed no statistical interaction between diabetes and three SNPs in HNFIB/TCF2." (PMID 21390317, 2011).
type 2 diabetes (30 papers, 2008 to 2025). "Low birth weight synergizes with HHEX and JAZF1 risk alleles to increase type 2 diabetes susceptibility." (PMID 41190158, 2025). "JAZF1 has been previously implicated in GWAS for type 2 diabetes, body fat distribution, and body mass index." (PMID 38854080, 2024). "Juxtaposed with another zinc finger protein 1 (JAZF1) is a transcriptional coregulator associated with pathophysiological processes in type 2 diabetes, as confirmed by animal studies." (PMID 37540242, 2023). "Studies have demonstrated that JAZF‐1 polymorphism is significantly associated with the progression of type 2 diabetes, and JAZF‐1 overexpression enhances glucose tolerance and insulin sensitivity." (PMID 36734198, 2023). "A recent GWAS found two genetic variants in JAZF1, one with a major allele predisposing to type 2 diabetes and the other with a major allele protecting against prostate cancer." (PMID 32705315, 2020). "Genetic variants in JAZF1 (encoding JAZF zinc finger 1) also have an inverse effect on the relationship between type 2 diabetes and prostate cancer." (PMID 32705315, 2020). "Several locus-specific scores for type 2 diabetes, including JAZF1 and TCF7L2, are associated with C-peptide persistence." (PMID 31438962, 2019). "The strongest associated AIM, although not showing a robust enough association to overcome a Bonferroni correction for multiple testing, rs10486576, is located in the JAZF1 locus, a gene implicated in type 2 diabetes (T2D), height and prostate cancer." (PMID 25783644, 2015). "A very recently published study investigated associations of the type 2 diabetes risk alleles in JAZF1, CDC123/CAMK1D, TSPAN8/LGR5, THADA, ADAMTS9, and NOTCH2 with obesity, insulin sensitivity, and insulin secretion in 4516 Danes." (PMID 18714373, 2008). "The human JAZF1 locus is notoriously associated with type 2 diabetes (T2D)." (PMID 37091973, 2023). "Previous studies have shown that polymorphisms of ADCY5, CAPN10, and JAZF1 genes may be associated with an increased risk of type 2 diabetes." (PMID 34440550, 2021). "Interestingly, one such gene, the transcription factor Jazf1, is associated with the development of type 2 diabetes." (PMID 25053427, 2014). "Interestingly, common variants in JAZF1 were also recently implicated in type 2 diabetes and prostate cancer susceptibility, in line with evidence for pleiotropic effects at many common disease loci." (PMID 19343178, 2009). "In the initial GWA meta-analysis the JAZF1 variant showed the strongest association with type 2 diabetes and the same variant has subsequently shown association with decreased BIGTT-AIR an estimate of serum insulin release following an OGTT in middle-aged Danes." (PMID 19789630, 2009). "This study aims to reveal the association between JAZF1 rs864745 A>G variant and type 2 diabetes (T2D), type 1 diabetes (T1D) risk, and their correlation with clinical features, including islet function, islet autoimmunity, and plasma lipid levels." (PMID 35846288, 2022). "The SNV at the JAZF1 locus was highly pleiotropic, as shown by associations with several autoimmune disorders (systemic lupus erythematosus, Crohn’s disease and selective immunoglobulin A deficiency), height, type 2 diabetes and JAZF1 transcript levels in adipose tissue." (PMID 28379579, 2017). "Genome-wide association studies (GWAS) have shown that the risk A allele of rs864745, an intron variant in JAZF1, correlates with both type 1 (T1D) in Europeans, and type 2 diabetes (T2D) in various ethnicities, including Europeans, Americans, as well as Asians." (PMID 35846288, 2022). "Previous studies investigated in various populations the associations between the polymorphisms of the ADCY5 gene (rs11708067, rs2877716), CAPN10 gene (rs2975760, rs3792267), JAZF1 gene rs864745, and type 2 diabetes." (PMID 34440550, 2021). "Reduced JAZF1 expression was also noted in mice on high-fat diets and patients with type 2 diabetes." (PMID 34440550, 2021).
type 2 diabetes (continued). "Juxtaposed with another zinc finger protein 1 (Jazf1) is a zinc finger protein and is known to affect both prostate cancer and type 2 diabetes." (PMID 29416651, 2018). "Consistent with a pathogenic role in islets, it has recently been shown that JAZF1 expression is reduced in individuals with type 2 diabetes or hyperglycemia, and that JAZF1 expression was correlated with insulin secretion." (PMID 23442068, 2013). "And meta-analysis on three Caucasian GWAS yielded six additional loci (JAZF1, TSPAN8-LGR5, THADA, ADAMTS9, NOTCH2-ADAM30 and CDC123-CAMK1D) associated with type 2 diabetes at genome-wide statistic significance." (PMID 19862325, 2009). "The GWAS SNPs may affect the expression of Jazf1 in adipose tissue, suggesting that its function in this tissue may be important for its role in type 2 diabetes." (PMID 23442068, 2013). "Furthermore, a meta-analysis of three GWASs detected six novel variants (in JAZF1, CDC123/CAMK1D, TSPAN8/LGR5, THADA, ADAMTS9, and NOTCH2) that were associated with type 2 diabetes." (PMID 20161779, 2010). "However, it is not unexpected that our study was unable to find significant associations between SNPs in JAZF1, CDC123/CAMK1D, TSPAN8/LGR5 and ADAMTS9 and type 2 diabetes, since the meta-analysis required more than 9000 samples for an 80% power." (PMID 20161779, 2010). "Quantitative- and metabolic-characteristics of 820 non-diabetic offspring of type 2 diabetes patients, stratified according to genotype of JAZF1 rs864745." (PMID 19789630, 2009).
endometrial stromal sarcomas (21 papers, 2010 to 2025). "The JAZF1/JJAZ1 fusion gene is frequently present in classical endometrial stromal sarcomas and less often in cases with variant histology." (PMID 20368795, 2010). "Additionally, Jazf1 is associated with tumor progression, including endometrial stromal sarcoma and prostate cancer." (PMID 29416651, 2018). "Recently, it has been reported that JAZF1 also regulates biological functions in human tumors, particularly in endometrial stromal sarcomas and prostate cancer." (PMID 40866818, 2025). "The majority of low-grade endometrial stromal sarcomas (LG-ESSs) harbor a fusion gene, most commonly involving JAZF1, SUZ12, and/or PHF1 genes, i.e., JAZF1-SUZ12 fusion (80%), JAZF1-PHF1 fusion (6%), or EPC1-PHF1 fusion (4%)." (PMID 32921307, 2020). "An oncogenic fusion gene, JAZF1/JJAZ1 plays a significant role in tumor development of endometrial stromal sarcomas." (PMID 20368795, 2010). "Additionally, it has been reported that JAZF1 functions in tumour progression in endometrial stromal sarcoma and prostate cancer." (PMID 31357957, 2019). "In addition, Jazf1 affects human cancers, especially prostate cancer and endometrial stromal sarcomas." (PMID 29416651, 2018). "Intriguingly, endometrial stromal sarcomas frequently involve rearrangements of the JAZF1 locus." (PMID 24497837, 2014). "Also, we noted a significant predominance of simple genomic sarcoma in long‐term survivor (54%) and, more specifically, of translocation‐related sarcoma (90%) especially SSX‐SS18 or JAZF1 fusion transcript, consistently with frequent synovial sarcomas and endometrial stromal sarcomas." (PMID 30916474, 2019). "The presence of the JAZF1/JJAZ1 fusion gene within the spectrum of endometrial stromal tumors from benign to malignant raises possibility that the endometrial stromal nodule may transform into malignant endometrial stromal sarcoma." (PMID 20368795, 2010). "For endometrial neoplasms with a malignant mesenchymal component, C-MYC mutations and loss of heterozygosity are frequently seen in carcinosarcomas, and a fusion gene, JAZF1/JJAZ1, is distinctive for endometrial stromal sarcoma." (PMID 20368795, 2010). "No PHF1 and JAZF1 break-apart signals did not support the diagnosis of low grade endometrioid stromal sarcoma, in which, more than 50% cases harbor gene fusions." (PMID 32290854, 2020). "Although the JAZF1/JJAZ1 fusion gene seems to be the major molecular alterations in endometrial stromal sarcomas, there is some evidence for alternative pathways in the development of endometrial stromal sarcomas." (PMID 20368795, 2010). "However, fluorescence in situ hybridization (FISH) for the JAZF1 gene rearrangement was negative, which helped exclude the possibility of metastatic low-grade endometrial stromal sarcoma." (PMID 40868224, 2025). "Although JAZF1/JJAZ1 fusion may not be universally present in all low grade endometrial stromal sarcoma, this aberration may still be diagnostically useful." (PMID 20368795, 2010).